EGFR (epidermal growth factor receptor)
Diseases named in the same sentence as EGFR in open-access papers (continued):
Sharing a sentence is not in itself a finding about the gene and the disease.
glioma (continued). "In Drosophila, a combination of EGFR and PI3K mutations effectively causes a glioma-like condition that reproduces the features of human gliomas including glia expansion, brain invasion, neuron dysfunction, synapse loss and neurodegeneration." (PMID 32878880, 2020). "Here, we demonstrate that SH3KBP1 interacts physically with EGFR, thereby promoting EGFR activation and glioma tumorigenesis in vitro and in vivo." (PMID 33643898, 2020). "In glioma, epidermal growth factor receptor (EGFR) activation increases 6PGD phosphorylation and activation to promote DNA synthesis and resistance to radiation." (PMID 32582032, 2020). "Further experiments are needed to elucidate the effect of TNuF on EGFR and PD-L1 expressions in glioma or head and neck cancer cells in the context of the same animal system." (PMID 32872195, 2020). "These gliomas were all wild-type for Idh1, consistent with gliomas in humans in which IDH1 and EGFR mutations tend to be mutually exclusive." (PMID 32727536, 2020). "A combination of EGFR activation and inactivation of Ink4a/Arf, which are common co-occurring genetic alterations observed in high-grade gliomas, has been shown to play a role in dedifferentiation of astrocytes through the process of gliomagenesis." (PMID 31992716, 2020). "For example, miR-181b regulated the chemosensitivity of glioma to temozolomide by targeting Bcl-2 and EGFR." (PMID 32061256, 2020). "Frequent driver mutations and amplifications of EGFR, including extrachromosomal ones, have also been detected in IDH1 wild-type, histologically low-grade gliomas (LGGs)." (PMID 32727536, 2020). "In the present study, whole-genome CNVs of glioma were detected in the TCGA datasets, and the most common amplification events on chromosome 7 (EGFR/MET) were found at high frequencies in GBM, consistent with previous reports." (PMID 32001707, 2020). "GISTIC 2.0 analysis identified several significant regions of amplification harboring multiple oncogenes in gliomas with a high-risk score, including 1q32.1 (PIK3C2B), 4q12 (PDGFRA), 7p11·2 (EGFR), and 12q14·1(CDK4)." (PMID 32023222, 2020). "In glioma cells, pharmacological EGFR blockade confers protection from hypoxia-induced cell death, and starvation conditions attenuated the cytotoxic effect of EGFR inhibition." (PMID 33092032, 2020). "Over-expression of EGFR was found in more than 60% of primary GBM cases and is linked to the proliferation, angiogenesis and invasiveness of glioma cells." (PMID 32592373, 2020). "used anti-EGFR antibody-conjugated metal chelates in SPECT to image EGFR expression in mice bearing glioma cell lines." (PMID 33193439, 2020). "Go analysis predicted that WNT5A regulated molecular functions including GTPase activity, biological processes such as signal translation, and biological pathways such as EGFR-dependent signaling events in glioma." (PMID 32181818, 2020). "The newly established roles of SH3KBP1 in EGFR-driven tumorigenesis provide a rationale for SH3KBP1 as a novel prognostic marker for patients with glioma and a potential target for further therapeutic investigation." (PMID 33643898, 2020). "Treatment-resistant brain tumors, such as grade IV gliomas, overexpress epidermal growth factor receptor (EGFR) and galectin-1, leading to chemotherapy resistance." (PMID 32849207, 2020). "Our panel of cell lines deliberately represented a heterogeneous collection of different glioma subtypes, including both IDH1-wildtype and IDH1-mutated cells lines as well as one line that exhibits high-level EGFR amplification and expresses EGFRvIII." (PMID 32178271, 2020). "The detection of several molecular markers, including IDH1 mutation, 1p/19q codeletion, MGMT promoter methylation status, and EGFR amplification has been applied with clinical diagnoses of gliomas." (PMID 33692940, 2020).
glioma (continued). "In glioma cells, the C-terminus of EGFR directly interacts with the central part of Slc7a11 and stabilizes Slc7a11 cell surface expression, thereby suggesting a role in oncogenic signaling." (PMID 32587657, 2020). "In order to investigate the mechanism of EGFR relocalisation, glioma cells were pre-incubated with the endocytosis inhibitor Dynasore before Torin1 stimulation and analysed after 6 and 24 h." (PMID 32823532, 2020). "All these findings illustrated that LPP-AS2 plays an oncogenic role in glioma progression through EGFR." (PMID 32962742, 2020). "Taken together, glioma-derived exosomal miR-148a-3p promoted tumor angiogenesis through activation of the EGFR/MAPK signaling pathway by ERRFI1 inhibition." (PMID 33117083, 2020). "In summary, our results demonstrate that TMEM167A is essential for the function of acidic vesicles, which are necessary for the maintenance of the EGFR–AKT axis in glioma cells." (PMID 31947645, 2020). "The EM/PM subtype is another glioma molecular classification based on the coexpression modules of EGFR and PDGFRA." (PMID 33575206, 2020). "Restoration/downregulation of LPP-AS2 expression partially rescued the suppressive/accelerated effects of EGFR knockdown/overexpression on glioma cell apoptosis." (PMID 32962742, 2020). "Amplifications of the epidermal growth factor receptor (EGFR) are frequent events in high-grade glioma." (PMID 32705082, 2020). "Competitive binding assay (CBA) demonstrated that C225–G5–MTX exhibited a higher affinity for the EGFR-expressing rat glioma cell line (F98EGFR) than the wild-type rat glioma cell line (F98WT)." (PMID 33321953, 2020). "Other researchers described the HSP90-dependent expression of EGFR, EGFRvIII, and Akt in glioma SCs, which was required for their proliferation, migration, and survival, and also for angiogenesis." (PMID 32268506, 2020). "GATA2, hematopoietic factor and gain of function assay revealed that GATA2 significantly enhanced proliferation, migration and invasion of glioma cells by activating EGFR signaling." (PMID 33643898, 2020). "Understanding the driver landscapes in the context of mutant EGFR is essential for advancing targeted glioma therapies." (PMID 32727536, 2020). "Altogether, piggyBac mutagenesis has comprehensively identified known and novel putative cancer genes and pathways driving EGFR-mutant gliomas." (PMID 32727536, 2020). "A study has shown that the binding of EGF to EGFR in human glioma cells induces tyrosine kinase-dependent Ca2+ oscillations." (PMID 32841278, 2020). "Generally, EGFR overexpression in gliomas has been mainly recognized to gene amplification, the activating mutation EGFRvIII, and gene fusion events, which overall comprise approximately half of GBM and are rarely observed in LGG." (PMID 33321953, 2020). "FBLN2, FBLN3, and FBLN5 have been shown to regulate Notch, Insulin Growth Factor receptor (IGF1R), EGFR signaling pathways, respectively, in glioma, lung, and pancreatic cancers." (PMID 32719793, 2020). "For that, we separated the TCGA glioma cohort in two groups (with low- and high-quantity of EGFR mRNA), and we analyzed the differential expression of a signature of genes associated with endosomes and vesicular transport." (PMID 31947645, 2020). "The most frequent genetic alterations/mutations found in gliomas are: hemizygous/homozygous deletion of NF-1 and PTEN; EGFR vIII mutant expression; and EGFR amplification." (PMID 32517694, 2020). "Using this method, significantly higher levels of EV EGFR were identified in 23 glioma patients compared to 12 healthy patients." (PMID 33143170, 2020). "LPP-AS2 was found to function as a ceRNA to regulate EGFR expression by sponging miR-7-5p in glioma cells." (PMID 32962742, 2020).
glioma (continued). "From the genes selected, known markers in glioma and GBM, namely SOX9 and EGFR, are here associated to astrocyte development and differentiation." (PMID 32070274, 2020). "In cluster I, the EGFR locus (chromosome 7p11.2, 14.3%) was significantly amplified, consistent with EGFR chromosomal amplification during glioma progression." (PMID 33194713, 2020). "For example, inhibition of EGFR/MAPK signaling pathway has been shown to suppress glioma activation." (PMID 33117083, 2020). "The inhibition of mTOR, a downstream molecule of the PI3K/PTEN/AKT pathway, promoted the response of glioma cells to EGFR-TKIs in vitro." (PMID 33321953, 2020). "Our research showed the low expression of miR-450a-5p and high expression of EGFR in glioma tissues." (PMID 32820249, 2020). "In contrast, these secondary genetic abnormalities are rare in IDH wild-type gliomas, while EGFR amplification appears to occur more frequently compared with IDH mutant gliomas." (PMID 32825279, 2020). "Then, we explore the significant correlation between AEBP1 upregulation and increased EGFR expression in primary glioma, and employ a glioma cell line LN229 to identify relevant proteins and molecular pathways through protein network analysis." (PMID 32938364, 2020). "The NPs not only penetrated the BBB but also silenced the expression of GOLPH3 mRNA and enhanced the expression of EGFR and pEGFR upon entering glioma cells." (PMID 33321953, 2020). "This highlights the important differences between the mechanisms of EGFR function in gliomas versus." (PMID 31947645, 2020). "EGFR is a prime target for therapy across a broad variety of tumor types including gliomas, suggesting NKG2A blockade with monalizumab has potential to boost NK cell-mediated ADCC against gliomas, particularly those resistant to TMZ." (PMID 32903717, 2020). "Similar to findings with TKIs, preclinical studies of cetuximab noted failure to alter EGFR downstream signal transduction in the context of gliomas, with reduction in cell viability achieved after inhibiting PI3K and MET pathways." (PMID 33187135, 2020). "In the de Novo pathway of glioma occurrence, two crucial oncogenes (EGFR and MDM2) and two important tumor suppressors (PTEN and IKN4a/ARF) were found to be closely correlated with WNT5A in glioma." (PMID 32181818, 2020). "The EGF receptor (EGFR) and its downstream signaling is frequently aberrant in cancers, especially in glioma." (PMID 33353229, 2020). "In fact, the epidermal growth factor receptor (EGFR) is a tumor-promoting receptor commonly amplified in gliomas, and the EGF-like growth factor (HBEGF) is a protein highly expressed in regulatory macrophages with immunosuppressive activity." (PMID 33155039, 2020). "The strength of the models here are molecular features recapitulating human EGFR-mutant gliomas, including the matched transcriptomic signatures and cooperative mutations." (PMID 32727536, 2020). "Other examples include PTEN mutation in SW1783 cells associated with resistance to the NAMPT (nicotinamide phosphoribosyltransferase) inhibitor daporinad in EGFR amplified low-grade glioma cell lines." (PMID 33205120, 2020). "Lastly, 11C-PD153035 PET/CT was demonstrated to be positively correlated with ex vivo EGFR immunostaining and Western blot analysis in the case of glioma patients (left)." (PMID 33193439, 2020).
glioma (continued). "AG490 is a Janus Kinase 2 (JAK2) inhibitor used for glioma therapy, but it also has inhibitory activity toward the epidermal growth factor receptor (EGFR) mediating PI3K/AKT signaling." (PMID 33172406, 2020). "In many cases, EGFR seems to control the neovascularization of glioma through the activation of NFκB or SRC (sarcoma)." (PMID 32570988, 2020). "Coamplification of CHCHD2 and the well-known GBM marker EGFR, also included in the gene signature, has been reported in glioma." (PMID 32070274, 2020). "A correlation between endocytic trafficking and GOLPH3-driven oncogenesis was suggested by a recent paper from Zhou and coauthors, which reported a role for GOLPH3 in glioma progression for inhibiting endocytosis and degradation of EGFR." (PMID 32023813, 2020). "Targeting FAK/STAT3 sensitizes gliomas to the anti-EGFR agent gefitinib and alkylating agent temozolomide in human gliomas." (PMID 32045997, 2020). "Although PDGFRA amplification is less common in gliomas than EGFR amplification, PDGFRA gene amplification is found in 11% of GBMs, making it the second most frequent RTK gene amplified in this family of tumors." (PMID 33081688, 2020). "In glioma, amplification of epidermal growth factor receptor (EGFR) and/or its constitutively active mutant form, EGFRvIII, promotes the expression of TF, PARs, and ectopic synthesis of FVII, thus sensitizing the cells to TF-mediated signaling." (PMID 32665005, 2020). "So far, all targeted treatment attempts in gliomas, e.g., targeting EGFR, have failed in clinical trials and effective treatment strategies are urgently needed." (PMID 33009951, 2020). "Glioma cells secrete EVs containing proteins (EGFR/EGFRvIII, MGMT and APNG) and RNAs (miR-21, miR-23, miR-29a, miR-30a, miR-221 and miR-451) to regulate the proliferation of recipient cells via several signaling pathways (AMPK, AKT, and MAPK) 54-57." (PMID 32550897, 2020). "Our preliminary study showed that miR-450a-5p was differentially expressed in gliomas, and was predicted to have binding sites on EGFR." (PMID 32820249, 2020). "EGFR has been extensively studied as a driver of gliomas in the past, and the association of this gene and transcript with outcome has been a matter of debate." (PMID 32573435, 2020). "Studies over MiR-34a revealed an anti-tumor effect on glioma cells by modifying epidermal growth factor receptor (EGFR) and PD-L1 expression." (PMID 32098401, 2020). "Our work elucidates functional driver landscapes of EGFR-mutant gliomas, uncovering potential therapeutic strategies, and provides new tools for functional interrogation of gliomagenesis." (PMID 32727536, 2020). "EGFR-inhibitors are commonly used in the treatment of different EGFR amplified cancers, including colorectal, lung, breast, pancreatic, renal, head and neck, gynecologic, prostate and central nervous system tumors." (PMID 33154952, 2020). "Further, MET activation is associated with resistance to EGFR- and VEGF-targeted therapy, and therefore, this pathway plays an important role in the formation and progression of gliomas." (PMID 31221203, 2019). "Our data indicate that EGFR is strongly and uniquely hypermethylated in IDHmut gliomas (Supplementary Spreadsheet); such silencing would likely diminish any selection pressure toward activating EGFR alterations." (PMID 31222125, 2019). "Down-regulation of LRIG1 aggravates the aggressive properties of glioma cells by activating the EGFR pathway." (PMID 30487162, 2019). "Pair-wise comparison of CNAs in the glioma-associated genes ALK, PDGFRA, VEGFR2/KDR, EGFR, MET and FGFR1 was performed employing MLPA techniques." (PMID 30894200, 2019).
glioma (continued). "The expression of EGFR in serum EVs can accurately differentiate high-grade and low-grade glioma patients, and EGFR in EVs positively correlates with ki-67 LI in the tumor tissue." (PMID 31410219, 2019). "Human U87 glioma cells, which overexpress the EGFR, were implanted, under stereotactic guidance, in the caudate-putamen nucleus (CPN) on one side of the brain of 20 g female SCID mice." (PMID 31998120, 2019). "We further performed paired comparisons of the expression of EGFR in EVs pre- and post-operation in each of the 8 glioma patients who underwent surgical resection." (PMID 31410219, 2019). "In melanoma, LRIG1 shows the same effects as glioma, but these are mediated by blocking via EGFR/ERK signaling." (PMID 31993365, 2019). "In human glioma tissues and cells, Ninj2 co-immunoprecipitated with multiple receptor tyrosine kinases (EGFR, PDGFRβ and FGFR), required for downstream Akt and Erk activation." (PMID 31794427, 2019). "We found high expression levels of EGFR in EVs derived from glioma cells and demonstrated that EGFR+ serum EVs can be used to diagnose glioma patients with high sensitivity and specificity." (PMID 31410219, 2019). "EGFRvIII is a unique EGFR mutant subtype in glioma, and the CRISPR‐Cas13a system induces death in EGFRvIII‐overexpressing glioma cells." (PMID 31637166, 2019). "Classical glioma is characterized by amplification of epidermal growth factor receptor (EGFR) gene, which leads to EGFR protein overexpression." (PMID 30782784, 2019). "We focus on the expression of epidermal growth factor receptor (EGFR), which is a transmembrane tyrosine kinase that regulates cell proliferation, migration and differentiation, in EVs from glioma patients, as EGFR is a common marker for glioma." (PMID 31410219, 2019). "Inhibition of mTOR, a downstream molecule of the PI3 kinase/PTEN/AKT pathway, promoted the response of glioma cells to EGFR-TKIs in vitro." (PMID 31284441, 2019). "Utilization of tissue microarrays of canine glioma for immunohistochemistry has revealed overexpression of EGFR, PDGFRα, IGFBP2 with EGFR expression moderately correlated to Ki67 immunoreactivity." (PMID 31788444, 2019). "The outcomes indicated that CED was more effective than intratumoural injection to deliver boronated EGF to EGFR(+) gliomas for boron neutron capture therapy." (PMID 31783573, 2019). "EGFR inhibitors, including gefitinib and erlotinib, also increase PpIX synthesis in glioma cells in vitro through blockage of the ATP binding cassette subfamily G member 2 (ABCG2) transporter." (PMID 31847378, 2019). "Activation of Wnt/β-catenin/Tcf signaling pathway was found in human glioma and interruption of β-catenin suppresses the epidermal growth factor receptor pathway by blocking multiple oncogenic targets in human glioma cells." (PMID 31596734, 2019). "In contrast, several other studies demonstrated that LRIG3 inhibited the proliferation, apoptosis, and invasion of glioma cells by negatively regulating the EGFR signaling pathway." (PMID 31245283, 2019). "In glioma cells, PTPRK is involved in epidermal growth factor receptor (EGFR) and b-catenin dephosphorylation and loss of PTPRK activity results in increased EGFR and b-catenin phosphorylation." (PMID 31027318, 2019). "It has been shown that Akt signaling is highly activated in many gliomas, mediated by the overexpression of receptor tyrosine kinases, i.e., epidermal growth factor receptor (EGFR) and platelet derived growth factor receptor (PDGFR)." (PMID 31003476, 2019). "Two phase II clinical trials on recurrent EGFR-amplified glioma have been carried out (NCT01520870 and NCT01112527)." (PMID 30782784, 2019).